TCP11 (t-complex 11)
Description:
Plays a role in the process of sperm capacitation and acrosome reactions. Probable receptor for the putative fertilization-promoting peptide (FPP) at the sperm membrane that may modulate the activity of the adenylyl cyclase cAMP pathway.
Synonyms: KIAA0229; FPPR; D6S230E
Tractability: Antibody: UniProt predicts a signal peptide or a membrane-spanning region.
Gene: Protein-coding gene on chromosome 6 (35,118,071 to 35,148,610, reverse strand). Ensembl gene ENSG00000124678.
Subcellular location: Membrane; Cell projection, cilium, flagellum; Cytoplasmic vesicle, secretory vesicle, acrosome
Gene Ontology:
Biological process: germ cell development; adenylate cyclase-activating G protein-coupled receptor signaling pathway; cAMP/PKA signal transduction; regulation of sperm capacitation; signal transduction
Cellular component: acrosomal vesicle; sperm flagellum; sperm midpiece; membrane; motile cilium
Genetic constraint (gnomAD): Loss-of-function variants: 32 observed, 45.35 expected, observed/expected ratio (o/e) 0.71, 90% interval 0.53 to 0.95. The upper end of that interval is the gene's LOEUF score, 0.95, which puts it in group 4 of 6, group 1 being the genes least tolerant of losing a copy. Missense variants: 518 observed, 618.74 expected, observed/expected ratio (o/e) 0.84, 90% interval 0.78 to 0.9. Synonymous variants: 226 observed, 238.23 expected, observed/expected ratio (o/e) 0.95, 90% interval 0.85 to 1.06.
Homologues: Orthologues: chimpanzee TCP11 (85% identical), rabbit TCP11 (84% identical), dog TCP11 (83% identical), pig TCP11 (79% identical), macaque TCP11 (77% identical), rat Tcp11 (72% identical), mouse Tcp11 (71% identical), guinea pig TCP11 (67% identical), Drosophila melanogaster CG16721 (26% identical), Caenorhabditis elegans M05D6.2 (23% identical). Paralogues in human: TCP11X2 (69% identical), TCP11X1 (69% identical), TCP11L1 (39% identical), TCP11L2 (37% identical).
Diseases named in the same sentence as TCP11 in open-access papers:
TCP11 is named in the same sentence as 9 diseases in open-access papers, as found by Europe PMC text mining. Sharing a sentence is not in itself a finding about the gene and the disease. The quoted sentences say what the papers report.
asthenozoospermia (1 paper, 2020). "We have previously reported on genes whose KO led to asthenozoospermia, such as Tektin 3 (TEKT3), Tektin 4 (TEKT4), T-complex-associated-testis-expressed 1 (TCTE1), and T-complex 11 (TCP11), with each having unique roles in sperm motility." (PMID 32588889, 2020).
cervical cancer (1 paper, 2023). A primary or metastatic malignant neoplasm involving the cervix. "However, the effect of TCP11 gene on the proliferation, apoptosis and migration of cervical cancer cells and its underlying molecular mechanisms are unclear." (PMID 37697257, 2023). "TCP11 gene can affect the proliferation and migration of cervical cancer cells, possibly by affecting the expression of cell cycle related molecules and EMT related molecules." (PMID 37697257, 2023). "GEPIA database, tissue microarray, western blot and qRT-PCR were used to analyze the expression of TCP11 gene in cervical cancer tissues and cells and its relationship with patients’ survival rate." (PMID 37697257, 2023). "After lentivirus infection with cervical cancer HeLa and SiHa cells, the expression of TCP11 protein and mRNA was detected to confirm the successful selection of stably transfected cells overexpressing TCP11." (PMID 37697257, 2023). "To initially explore the role of TCP11 in cervical cancer, we used GEPIA database for predictive analysis." (PMID 37697257, 2023). "Compared with immortalized epithelial HaCaT cells, TCP11 protein and mRNA were highly expressed in three cervical cancer cell lines." (PMID 37697257, 2023). "The results showed that TCP11 gene was highly expressed in cervical cancer tissues and cells compared with normal cervical tissues and cells, and its expression was positively correlated with patients’ survival rate." (PMID 37697257, 2023). "In this study, through GEPIA database and tissue microarray assay, we demonstrated that the expression of TCP11 gene was higher in cervical cancer tissues than in normal cervical tissues." (PMID 37697257, 2023). "Further research is needed on the proliferation and migration effects of TCP11 gene on cervical cancer cells." (PMID 37697257, 2023). "In order to better understand the potential reasons of TCP11 promoting apoptosis of cervical cancer cells, we used western blot to analyze the protein expression of apoptosis-related molecules caspase-3, cleaved-caspase-3 and cleaved-PARP." (PMID 37697257, 2023). "We found that overexpression of TCP11 arrested the cell cycle of cervical cancer cells, HeLa cells were arrested in G2/M phase, SiHa cells were arrested in S phase." (PMID 37697257, 2023). "The previous gene microarray results found that the expression of TCP11 gene in cervical cancer tissue was significantly higher than that in normal cervical tissue." (PMID 37697257, 2023). "In summary, our results suggest that TCP11 plays an important role in the development of cervical cancer." (PMID 37697257, 2023). "TCP11 overexpression can inhibit the proliferation and migration of cervical cancer cells, block cell cycle and induce apoptosis." (PMID 37697257, 2023). "The expression of TCP11 protein in cervical cancer tissues was higher than that in normal cervical tissues." (PMID 37697257, 2023). "The results showed that the mRNA expression of TCP11 in cervical cancer tissues was higher than that in normal cervical tissues." (PMID 37697257, 2023). "TCP11 overexpression significantly inhibited the expression of Ki67 in cervical cancer cells." (PMID 37697257, 2023). "However, we still need to further study which specific signaling pathway can regulate the inhibitory effect of TCP11 on cervical cancer progression." (PMID 37697257, 2023). "Flow cytometry was used to analyze whether the expression of TCP11 has an effect on the apoptosis of cervical cancer cells." (PMID 37697257, 2023). "In addition, western blot and qRT-PCR were used to detect the expression of TCP11 protein and mRNA in immortalized epithelial cells HaCaT and cervical cancer HeLa, SiHa and C33A cells, respectively." (PMID 37697257, 2023). "Interestingly, GEPIA database analysis showed that TCP11 gene was highly expressed in cervical cancer, and its high expression was beneficial to the prognosis of cervical cancer patients." (PMID 37697257, 2023).
cervical cancer (continued). "Furthermore, we found that TCP11 overexpression significantly inhibited the proliferation and migration of cervical cancer HeLa and SiHa cells." (PMID 37697257, 2023). "To further investigate whether TCP11 inhibits the migration of cervical cancer cells by regulating EMT, we detected the protein and mRNA expressions of EMT-related molecules ZO-1 and E-cadherin." (PMID 37697257, 2023). "Analysis of the expression changes of EMT-related molecules could reveal the potential reasons of TCP11 gene affecting cervical cancer cell migration." (PMID 37697257, 2023). "TCP11 overexpression significantly inhibited the occurrence and development of cervical cancer cells, it may be a potentially beneficial biomarker for cervical cancer." (PMID 37697257, 2023). "Gene microarray found that TCP11 gene was highly expressed in cervical cancer." (PMID 37697257, 2023). "The study revealed that TCP11 may be a potential biomarker of cervical cancer, playing a role in the prevention, treatment and analysis of cervical cancer prognosis." (PMID 37697257, 2023). "Interestingly, based on the GEPIA database, we found that cervical cancer patients with high expression of TCP11 had significantly higher overall survival than those with low expression." (PMID 37697257, 2023). "To confirm the role of TCP11 in cervical cancer, we first investigated whether overexpression of TCP11 by lentivirus infection had an effect on the proliferation of cervical cancer cells." (PMID 37697257, 2023). "This suggests that TCP11 may inhibit the migration of cervical cancer cells by increasing tight junctions and adhesion between cells." (PMID 37697257, 2023). "But, the effect of TCP11 gene on the development of cervical cancer remains unclear." (PMID 37697257, 2023). "This suggests that TCP11 may be a prognostic indicator for cervical cancer patients." (PMID 37697257, 2023). "Therefore, we speculated whether TCP11 gene could inhibit the progression of cervical cancer cells by regulating the activity of cAMP/PKA signaling pathway." (PMID 37697257, 2023). "Interestingly, cervical cancer patients with high expression of TCP11 had higher survival rates." (PMID 37697257, 2023). "TCP11 may be a potentially beneficial biomarker for cervical cancer." (PMID 37697257, 2023). "It is worth noting that the TCP11 had low expression in testicular germ cell tumor in GEPIA database, which was contrary to the high expression in cervical cancer." (PMID 37697257, 2023). "The results showed that TCP11 overexpression can inhibit the EMT process by increasing the protein and mRNA expressions of ZO-1 and E-cadherin, thereby inhibiting the migration of cervical cancer cells." (PMID 37697257, 2023). "We speculate that TCP11 gene may block the cell cycle by regulating the expression of CDK1/Cyclin B1, thereby inhibiting the proliferation of cervical cancer cells." (PMID 37697257, 2023). "In 31 cases of normal cervical tissue, the weak positive rate of TCP11 expression was 48.39%, and the negative rate was 51.61%; in 35 cases of cervical cancer tissue, the positive rate of TCP11 expression was 14.29%, the weak positive rate was 57.14%, and the negative rate was 28.57%." (PMID 37697257, 2023). "However, TCP11 gene was not reported in cervical cancer, which aroused our research interest." (PMID 37697257, 2023).
infertile (1 paper, 2020). "A previous report has correlated human TCP11 with sperm morphology, where sperm from infertile men that display aberrant morphology has less TCP11, and proteomics analysis identified TCP11 in the flagellum of human sperm." (PMID 31837139, 2020).
male infertility (1 paper, 2015). The inability of the male to effect fertilization of an ovum after a specified period of unprotected intercourse. "We observed differential expression of a number of transcripts, such as PRM1, SPATA18, TNP1, EIF4G2, CANX, RANBP9, TCP11, which have previously been associated with male infertility." (PMID 25973848, 2015).
varicocele (1 paper, 2023). A condition characterized by the dilated tortuous veins of the spermatic cord with a marked left-sided predominance. "TCP11 is overexpressed in bilateral varicocele patients, which can be used as a potential biomarker for bilateral varicocele." (PMID 37697257, 2023).
tumor (1 paper, 2018). "In contrast, the decreased expression of Tcp11, a determinant of sperm morphology, as well as the decreased expression of Stx11, a gene involved in tumor suppression, suggest roles for these factors in the small eye phenotype of the Cryaa-R49C-homo lenses." (PMID 29338044, 2018).
TCP11 also shares sentences with these, for which no sentence is quoted: Azoospermia (1 paper); lentivirus infection (1); testicular germ cell tumor (1).